INS (insulin)
Diseases named in the same sentence as INS in open-access papers (continued):
Sharing a sentence is not in itself a finding about the gene and the disease.
Obesity (continued). "To establish whether obesity involves activation of endogenous ciliary neurotrophic factor (CNTF) signalling, we evaluated its plasma levels in patients with obesity and correlated its values with the major clinical and haematological indices of obesity, insulin resistance and systemic inflammation." (PMID 35585213, 2022). "Although exercise could not regulate the diversity or community structure of gut microbiota, it could improve the abundance of certain microbiome genera including Coprococcus, Blautia, Lachnospiraceae and Dorea to increase insulin sensitivity in patients with obesity." (PMID 36219347, 2022). "Insulin sensitivity studies showed that the quantity of glucose required to induce hyperglycemia in cod-fed rats was much larger than that in casein-fed rats, indicating that it protected rats from developing obesity-related insulin resistance and glucose tolerance." (PMID 36033572, 2022). "In contrast, resting heart rate (RHR) can be easily measured by anyone without any special equipment and is highly associated with obesity, stress, sympathetic nervous system, insulin, maximal oxygen comsumption, physical strength, and levels of physical activity." (PMID 34990528, 2022). "Specifically, and because it is the largest insulin-sensitive tissue in the body, skeletal muscle has the primary role for whole-body glucose utilization, a process that is, however, impaired in humans with obesity and in the presence of distorted muscle proteome." (PMID 35350688, 2022). "The insulin mimetic action of PGG may potentially counter the probable anti-obesity effect of PGG." (PMID 35409415, 2022). "While these effects have classically been limited to opposing insulin’s effects to maintain euglycemia, the role glucagon plays in amino acid and lipid metabolism as well as maintaining energy homeostasis has identified its effects as potential targets in the treatment of diabetes and obesity." (PMID 36009454, 2022). "In this context, we hypothesized that improved insulin sensitivity through RT is accompanied by positive alterations in the redox state that attenuate inflammation in skeletal muscles under conditions of diet-induced obesity." (PMID 35683979, 2022). "This indicates that pituitary dysregulation of LH in obesity may be mediated through insulin." (PMID 36320802, 2022). "Exercise has been shown to reduce TLR4 expression in rats with diet-induced obesity, with both acute and chronic exercise causing a significant suppression in the TLR4 signaling pathway in the muscle, liver, and adipose tissue and improvement of insulin signaling and sensitivity." (PMID 36360622, 2022). "The physiology-dependent mechanism believes that the physiological components of obesity, including blood sugar control, insulin action and leptin signaling, may lead to respiratory disturbances and increased central sleep apnea by reducing chemical sensitivity." (PMID 35923456, 2022). "Individuals with obesity may be less sensitive to IN insulin and have cerebral insulin resistance." (PMID 35397638, 2022). "Notably, the decreases in insulin sensitivity were greater among four LKDs with obesity." (PMID 36399462, 2022). "Hyperglycemia may be due to drugs that are known to cause hyperglycemia like VPA or due to a combination of MS risk factors commonly found among patients with epilepsy like obesity and lower exercise capacity that make body cells less sensitive or resistant to insulin." (PMID 36580471, 2022). "However, their numbers are significantly decreased in the insulin resistant models of obesity." (PMID 36292751, 2022). "As indicated in previous literature, an intensive intervention with a goal of reducing zBMI ≥ 0.5 may be needed to increase insulin sensitivity in children with obesity in the pubertal stage, and interventions with aerobic training components could be helpful in ameliorating insulin resistance." (PMID 35057568, 2022).
Obesity (continued). "Hence, it may be assumed that the impact of obesity on the ghrelin level dominates over the impact of OSA (probably via insulin levels)." (PMID 35407646, 2022). "The higher insulin levels in the DIO2 Ala/Ala genotype may be secondary to obesity." (PMID 36291357, 2022). "Additionally, plasma insulin levels post glucose load were significantly reduced in children with obesity practicing sport activity, while post load glucose levels were not modulated, suggesting that physical exercise is responsible for modulating systemic metabolic parameters in a specific manner." (PMID 36613885, 2022). "In addition, obesity can cause the body’s resistance to insulin, mediated in part by free fatty acids (FFA) and adipokines such as retinol binding protein-4 (RBP4) and resistin, which can reduce insulin sensitivity." (PMID 35216172, 2022). "Thus, overexpression of REDD1KKAA did not induce NF-κB activation, preadipocyte differentiation, and cytokine production in vitro; similar to Redd1−/− mice, Redd1KKAA mice presented restrained obesity-induced characteristics, including proinflammatory cytokine production and insulin resistance." (PMID 36272977, 2022). "However, others have shown that XPro1595 can improve diet induced obesity (high-fat high-carbohydrate diet) and central-peripheral insulin impairment, in wild type mice partly through dampening of hepatic lipocalin-2, which is associated with and elevated in liver steatosis." (PMID 36186984, 2022). "Furthermore, the chronic administration of a Fractaline analog in various rodent models of obesity improved glucose tolerance, increased β-cell glucose-stimulated insulin secretion, and reduced β-cell apoptosis, highlighting its positive effect in regulating glucose homeostasis." (PMID 35563026, 2022). "While others reported the regulation of glycogen synthesis is preserved after exercise in insulin‐resistant subjects, these data, along with our previously published work on dysregulated glycogen storage after exercise in adults with obesity, suggests more research is warranted." (PMID 36541258, 2022). "Hyperphagia alone does not explain all weight gain produced by elevated insulin levels, but may still contribute to the increased risk of obesity and T2D elicited by insulin hypersecretion." (PMID 36056607, 2022). "Indeed, increased liver production of LECT2 have been related to obesity development in rats, and resulting metabolic stress, which subsequently impairs insulin signaling, promote adhesion molecules expression, and increases pro-inflammatory cytokines synthesis." (PMID 34822062, 2022). "Furthermore, it has been suggested that a defect in this pathway could explain the simultaneous resistance to the appetite-suppressing effects of leptin and insulin in obesity." (PMID 35563589, 2022). "As obesity alters the fraction of hepatic insulin extraction, this may affect our results." (PMID 35501401, 2022). "Thus, obesity might be an important factor in modifying circulating levels of free-AGEs in an insulin-resistant state." (PMID 36432614, 2022). "Similar to insulin signaling, the thermogenic capacity of adipose tissue also depends upon the activity of various anti-inflammatory resident immune cells, which are impaired by inflammatory signaling cascades that are upregulated during obesity and decline in function with physiological aging." (PMID 34837070, 2022). "However, the contribution of obesity and sex on central insulin-mediated neural food cue processing still remains unclear." (PMID 35715625, 2022). "Given that effects of SGLT2i mimics catabolic state such as the increase of fat oxidation, ketone production and glucagon/insulin ratio, the administration of SGLT2i could be expected to enhance catabolic response during night and to restore dysregulated metabolic rhythm in obesity or T2DM patients." (PMID 36281369, 2022).
Obesity (continued). "Therefore, the tissues responsible for the bulk of whole body glucose metabolism, liver and muscle, were more likely to exhibit differences that contribute to our understanding of the maintenance of clamp insulin sensitivity in the presence of obesity in Hi-ST fed mice." (PMID 36394259, 2022). "However, these alterations in perfusion and endothelial structure do not affect insulin delivery to myocytes under normal physiological conditions, because the hyperinsulinemia associated with obesity compensates for this defect." (PMID 35054781, 2022). "Furthermore, while insulin is higher in obesity, cortisol (F), DHEA, and DHEAS appear to be lower." (PMID 35213912, 2022). "Decreased content of these trace elements in adipose tissue due to caloric excess has been hypothesised to lead to the development of adipose tissue insulin resistance through disruption of intra-adipocyte insulin signalling, and further adipokine imbalance that leads to obesity." (PMID 36430290, 2022). "Previous work showed that the skeletal muscle-enriched lncRNA H19 enhances muscle insulin sensitivity by activating AMPK, and the administration of H19 RNA increases the basal metabolic rate and protects against high-fat diet (HFD)- or leptin deficiency-induced obesity." (PMID 36604148, 2022). "Thus, A. muciniphila can reverse obesity induced by a high-fat diet, promote “passivation” of metabolic endotoxins, promote release of inflammatory bacterial lipopolysaccharides, and effectively reduce insulin resistance and heart metabolic complications." (PMID 36440358, 2022). "However, GIP may also act lipolitically by improving glucose tolerance, enhancing insulin sensitivity and reducing obesity-related pancreatic β-cells hyperplasia." (PMID 35205155, 2022). "ADF improved insulin signaling and altered the proportion of α and β cells in obese mouse pancreases by reducing β cell apoptosis, increasing Akt (serine/threonine) phosphorylation, and improving diet-induced obesity islet tissue remodeling and β cell function." (PMID 35565749, 2022). "However, the outcome of obesity on adipocyte lipid uptake is dependent on insulin signaling." (PMID 36111295, 2022). "In addition, obesity coexists with abnormal insulin action in most women with PCOS." (PMID 35012577, 2022). "Throughout the day, the insulin secretion rate from pancreatic β cells into the portal vein ranges from <200 pmol/min after an overnight fast in lean people to peak values of approximately 800 pmol/min postprandially in people with obesity and insulin resistance." (PMID 35054781, 2022). "Interestingly, we reported in male C57BL/6 J mice with obesity induced by high-fat/high-carbohydrate diet that prolonged-release pirfenidone decreased Nfe2l2 gene expression, and these mice showed improved systemic insulin sensitivity." (PMID 35204118, 2022). "4-HNE is not only associated with atherosclerosis but also with obesity, altering the lipid metabolism and accumulating in adipose tissue; although 4-HNE is not locally generated by the adipocytes, it penetrates adipose tissue from the blood, eventually being regulated by insulin and metformin." (PMID 35159254, 2022). "Although both humans and mice with obesity-associated hepatic steatosis display PTEN downregulation in the liver and usually IR, the total abrogation of PTEN in mouse livers, on the contrary, triggers muscle insulin hypersensitivity and decreased adiposity despite the presence of a large steatosis." (PMID 35409319, 2022). "In obesity, changes in the polarization state of macrophages in the adipose tissue, liver, and muscle were detected, and the interactions between macrophages and insulin target organs may influence both metabolism and inflammation." (PMID 36230963, 2022).
Obesity (continued). "Obesity is a critical risk factor for AF, and a dietary study in obese youth showed that a 12 week treatment with a diet characterized by a low n6:n3 polyunsaturated fatty acids (PUFA) ratio decreased hepatic fat levels, including triglycerides and LDL, with evidence of improved insulin sensitivity." (PMID 36418854, 2022). "Even though ATP11A’s involvement in obesity and T2D is unknown, there is evidence that deficient expression of some P4 ATPase family members, such as ATP10C and ATP10A, affects insulin-stimulated mobilization of GLUT4 vesicles to the plasma membrane or the regulation of insulin signaling." (PMID 36535927, 2022). "It has been proposed that visfatin production might potentially be low in the lean state and that intra-abdominal obesity leads to increased visfatin production, which simultaneously increases with obesity, but also changes the properties of visfatin, giving it more insulin-mimetic qualities." (PMID 35872989, 2022). "Hence, studying individual ROCK isoforms to elucidate their unique roles and mechanisms in white and beige adipogenesis, insulin sensitivity, and energy balance will facilitate significant breakthroughs in systemic application of isoform-selective inhibitors for obesity prevention and treatment." (PMID 35769086, 2022). "In this way, by coupling triglycerides to the glucose-insulin system the Mixed Meal Model provides a more holistic assessment of metabolic resilience from meal response data, quantifying pre-clinical metabolic deteriorations that drive disease development in overweight and obesity." (PMID 36281448, 2022). "Therefore, in this study, we examined the relationship between the mastication habits of Japanese people with obesity and the factors correlated with the obesity blood index, in relation to glucose metabolism and insulin resistance, by using a light-sensor-based mastication meter." (PMID 35889948, 2022). "The various environmental and biological factors that contribute to overweight and obesity in the general population, other than the insulin regimen, could partly explain the evolution of the prevalence of overweight and obesity in diabetic children and adolescents during the period studied." (PMID 35549683, 2022). "However, hyperinsulinemia concurrent with hyperaminoacidemia in subjects with obesity results in normal stimulation of protein synthesis in muscle, and although subjects with obesity are expected to have impaired insulin-stimulated blood flow in muscle." (PMID 35350688, 2022). "Similarly, in models of obesity, blueberry treatment improved insulin and glucose control." (PMID 35458181, 2022). "Women with polycystic ovaries reveal the clinical features of PCOS, including menstrual cycle disturbances, obesity, hirsutism, acne, and abnormality of biochemical profiles, such as elevated serum concentrations of LH, testosterone, androstenedione, and insulin." (PMID 35924049, 2022). "Several reports have suggested that statins may affect insulin sensitivity, but the results are controversial, showing either a beneficial, a neutral, or a worsening effect depending on the type/dose of these drugs and the co-existence of obesity." (PMID 35683611, 2022). "Experimental and clinical studies clearly demonstrate that increased glucose levels and impaired insulin signaling are potent drivers of the atherosclerotic process, even in the absence of concomitant risk factors such as hypertension, obesity, and dyslipidaemia." (PMID 35651853, 2022). "Moreover, the increased circulating levels of NTN-1 in obesity were associated with IR and the decrease of NTN-1 after caloric restriction was positively correlated with differences in glucose and insulin levels, suggesting the role of NTN-1 in the development of IR." (PMID 36297056, 2022).
Obesity (continued). "Our results are perfectly in line with data from the Yale Pediatric NAFLD cohort showing that intrahepatic lipid accumulation is associated with reduced insulin clearance and hepatic insulin sensitivity in youths with obesity, irrespective of their ethnic background." (PMID 35185803, 2022). "In addition, high fat diet-challenged TNFα-deficient mice had lower circulating free fatty acids and fasting insulin levels compared to control littermates, suggesting suppressing TNFα activity attenuated unfavorable lipolysis and hyperinsulinemia in diet-induced obesity." (PMID 35557517, 2022). "Thus, the Bbs12-/- mouse model (BBS12; a chaperone protein required for ciliogenesis during adipogenic differentiation of human mesenchymal cells) showed increased obesity, normal glucose tolerance and increased insulin sensitivity in the fat, recapitulating clinical features of BBS." (PMID 35832432, 2022). "Additionally, exercise also changes the proportion of fibers in SM; under obesity or IR conditions, type II fibers are the most abundant but could be reverted by exercise and, consequently, MAMs and insulin sensitivity." (PMID 36275635, 2022). "Moreover, using a myeloid cell-specific JNK1/2 double knock-out mouse model, another study demonstrated that macrophage JNK1/2 are required for the establishment of obesity-induced adipose tisse inflammation and insulin resistance through promoting macrophage M1 activation." (PMID 36119080, 2022). "Previous studies reported that DPP4 inhibitors could ameliorate high-fat diet-mediated obesity-related glomerulopathy, which may relate to the improved insulin sensitivity and reduced local inflammation through inhibiting macrophage infiltration and IL-6 and TNF-α secretion." (PMID 35935760, 2022). "AP-2β can target multiple features of obesity and T2D centrally and peripherally by modulating key-obesity linked genes such as IRS-1, GLUT4, adipocytokines related genes, as well as catecholaminergic and serotonergic genes involved in reward, consummatory behaviour and insulin resistance." (PMID 36076256, 2022). "This exploratory study underlines the difficulty in early prediction of GDM development in high-risk women but adds to the evidence that among pregnant women with obesity, insulin secretory dysfunction may be an important discriminator for those who develop GDM." (PMID 36295825, 2022). "Although adipose tissue-induced inflammation is low-grade, it has a negative effect on distal organ function through insulin resistance, which may be responsible for complications associated with obesity." (PMID 36419769, 2022). "In addition, individuals with obesity and impaired insulin sensitivity have higher levels of prostaglandin E2, indicating a state of chronic low-grade inflammation, which may interfere with tendon healing." (PMID 35774146, 2022). "Annexin A1 is known to have beneficial effects in islets by potentiating glucose‐stimulated insulin release and protecting against apoptosis, so its secretion from expanded adipose depots in obesity may lead to improved islet function via binding to the formylpeptide receptor FPR2." (PMID 36245259, 2022). "Increasing systemic TNF-α and IL-6 in obesity might impair insulin signaling pathway." (PMID 35409099, 2022). "Additionally, as a result of obesity, there is an increase in insulin resistance and adipogenesis." (PMID 36364814, 2022). "Based on these data, it would therefore be interesting to study whether fetuin-A, conveyed by EVs and released from vascular smooth muscle cells, could participate locally in the dysfunction of adipose tissue during obesity, altering insulin sensitivity in adipocytes and favoring inflammation." (PMID 35806052, 2022). "In addition, we explored whether IN insulin enhances cognitive performance, and predicted that any effects may be less pronounced in women with obesity." (PMID 35397638, 2022).